DNMT1 (DNA methyltransferase 1)
Diseases named in the same sentence as DNMT1 in open-access papers (continued):
Sharing a sentence is not in itself a finding about the gene and the disease.
synovial sarcoma (1 paper, 2025). "In our efforts to understand the mechanism of this sensitivity of synovial sarcoma to DNMT1 inhibitors, we tested a few potential mechanisms." (PMID 40299558, 2025). "We confirmed that application of purported DNMT1 inhibitors in synovial sarcoma cell lines strongly recapitulated the impact of DNMT1 gene disruption in transcription and cell morphology in tissue culture." (PMID 40299558, 2025). "However, single gene dependency testing identified only DNMT1 among those 2 gene groups as a particular point of vulnerability, even if the observed state of synovial sarcoma suggested relatively low activity of this enzyme in the cancer cells." (PMID 40299558, 2025). "We first investigated whether the genes that regulate DNA methylation (DNMT1, DNMT3A, DNMT3B, TET1, TET2, TET3) are misexpressed, mutated, or amplified in synovial sarcoma." (PMID 40299558, 2025). "This is not the case in synovial sarcoma, making its DNMT1 vulnerability somehow related instead to reduced baseline activity." (PMID 40299558, 2025).
teratoma (1 paper, 2018). A non-seminomatous germ cell tumor characterized by the presence of various tissues which correspond to the different germinal layers (endoderm, mesoderm, and ectoderm). "Although a number of phenotypes in Uhrf1 KO cells (i.e. cell death and small teratoma) overlapped with the Dnmt1 KO34, importantly we observed a number of unique features in this Uhrf1 KO study." (PMID 29968706, 2018).
Tetralogy of Fallot (1 paper, 2023). A congenital cardiac malformation comprising pulmonary stenosis, overriding aorta, ventricular septum defect, and right ventricular hypertrophy. "Several previous studies have shown that DNMT1 polymorphisms (rs16999593, rs2228612) are associated with the risk of developing CHDs, and that the decreased expression of DNMT1 may play an important role in the pathogenesis of tetralogy of Fallot." (PMID 36980848, 2023).
transient cerebral ischemia (1 paper, 2025). "The reduction in DNMT1 expression may be related to delayed neuronal death caused by transient cerebral ischemia." (PMID 40356977, 2025).
transitional cell carcinoma of the bladder (1 paper, 2018). "Increased DNMT1 expression has been reported in human transitional cell carcinoma of the bladder." (PMID 30526555, 2018).
urinary tract infection (1 paper, 2024). "In in vitro studies, urinary tract infection induced by Escherichia Coli resulted in increased DNMT1 activity, DNA methylation, and downregulation of the tumor suppressor gene CDKN2A." (PMID 38891848, 2024).
varicocele (1 paper, 2021). A condition characterized by the dilated tortuous veins of the spermatic cord with a marked left-sided predominance. "Percentage of DNMT1 positivesperm were similar between the two groups (fertile: 83.51± 3.00 vs. varicocele: 83.41 ± 2.3, P=0.97)." (PMID 34455713, 2021). "Among the analyzedcorrelations, positive significant correlations wereobserved between sperm concentration with percentage ofsperm DNMT1 protein in varicocele and total populationgroups." (PMID 34455713, 2021). "Incontrast to DNMT1, expression and percentage of DNMT3A and DNMT3B at RNA and protein levels were significantlyhigher in the varicocele group compared to the fertile group (P<0.05)." (PMID 34455713, 2021). "The relativefluorescence intensities of both DNMT1 (fertile: 72.03 ±8.00 vs. varicocele: 94.14 ± 10.3, P=0.11) and DMNT3A(fertile: 61.01 ± 16.5 vs. varicocele: 79.8 ± 16.3, P=0.43)were similar between the two groups." (PMID 34455713, 2021). "Our findings indicated that in contrast to the percentage of DNMT1 positive sperm, the mean percentagesof DNMT3A and DNMT3B positive sperm weresignificantly higher in varicocele group than fertilegroup." (PMID 34455713, 2021). "Localization of DNMT1, DNMT3A andDNMT3B enzymes were assessed in over 1000 spermfrom five pooled samples of only fertile individuals byfluorescence microscopy, not varicocele group." (PMID 34455713, 2021). "Negative correlationswere observed between percentage of sperm abnormalmorphology with percentage of DNMT1, DNMT3Aand DNMT3B positive sperm in varicocele group.Percentage of DNMT3A positive sperm also had negativesignificant correlation with percentage of sperm abnormalmorphology in fertile group." (PMID 34455713, 2021).
Varicose veins (1 paper, 2022). Enlarged and tortuous veins. "We found that both DNMT1 and DNMT3a were overexpressed in the endothelium of human varicose veins with blood reflux." (PMID 36293392, 2022). "DNMT1 and DNMT3a were overexpressed in the endothelium of human varicose veins with blood reflux (varicose vein F1)." (PMID 36293392, 2022).
vitamin B12 deficiency (1 paper, 2025). A disease characterized by low serum levels of vitamin B12, either inherited or acquired. "Vitamin B12 deficiency can alter DNA methylation, potentially leading to DNMT1 dysregulation." (PMID 39940809, 2025).
vitiligo (1 paper, 2018). Generalized well circumscribed patches of leukoderma that are generally distributed over symmetric body locations and is due to autoimmune destruction of melanocytes. "An aberrant mRNA expression of DNMT1 was also observed in PBMCs from vitiligo patients." (PMID 30254507, 2018).
cancer (1,033 papers, 2005 to 2026). A tumor composed of atypical neoplastic, often pleomorphic cells that invade other tissues. "High DNMT1 expression is especially prevalent in high-grade tumors, tamoxifen-resistant cancers, and TNBC subtypes, and it is linked to shorter overall survival (OS) and disease-free survival (DFS)." (PMID 41602389, 2026). "Studies also show that DNMT1 disruption in mice causes hypomethylation and chromosomal instability, which can drive cancer development." (PMID 40558829, 2025). "Previous studies have associated DNMT1 overexpression with tumorigenesis and metastasis in various cancers, and RASSF1A promoter hypermethylation has been implicated in its transcriptional silencing across multiple tumor types." (PMID 41381440, 2025). "Empirical investigations have revealed that herbal medicine exhibits the potential to regulate various ncRNAs and the DNMT1 axis, which are closely associated with cancer." (PMID 40387409, 2025). "Aberrant overexpression of DNMT1 has been widely reported across various cancers and is frequently associated with hypermethylation and silencing of tumor suppressor gene promoters." (PMID 40370966, 2025). "Over the last 20 years, evidence has progressively linked the involvement and importance of DNMT1 in tumorigenesis, aggressiveness and treatment response of human cancers." (PMID 40387409, 2025). "Antisense oligonucleotides targeting DNMT1, as well as experiments using DNMT1-deficient mice, have confirmed the enzyme’s central role in maintaining methylation patterns in cancer cells." (PMID 40806634, 2025). "Aberrant DNA methylation, catalyzed by DNMT1, is associated with various cancers by silencing of tumor suppressor genes, and is identified as a significant contributor to the advancement of cancer." (PMID 40050970, 2025). "Deletion of the DNMT1 gene rendered cancer cells susceptible to TET2 upregulation following exposure to DNMT inhibitors." (PMID 40675967, 2025). "While increased glycogen synthesis and glycogenolysis in cancer cells are typically associated with cancer progression, this study revealed unique findings regarding DNMT1-mediated glycogen deposition." (PMID 38755637, 2024). "The mechanisms underpinning the essentiality of UHRF1 and DNMT1 for long-term cancer cell proliferation have been suggested to be linked with their role in DNA methylation homeostasis." (PMID 38580649, 2024). "DNMT1 is commonly overexpressed in various cancers and is often linked to poor patient prognosis, as indicated by previous studies." (PMID 38755637, 2024). "Through CRISPR Cas9, the anti-tumor effect can be greatly improved through knockout of cancer-causing genes, such as DNA methyltransferase 1 (DNMT1) gene, survivine gene, and EGFR gene." (PMID 39407665, 2024). "The DNA methylation pattern mediated by DNMT1 has been reported to be implicated in various diseases, especially cancers;30 it is considered as a potential therapeutic target in some cancer cases." (PMID 38545254, 2024). "DNMT1 overexpression was accompanied by the accumulation of cancer-specific DNA hypomethylation during oral carcinogenesis; conversely, DNMT1 knockdown caused atypically extensive genome-wide DNA hypomethylation in cancer cells and xenografted tumors." (PMID 38755637, 2024). "DNMT1—Located on human chromosome 19p13.2, DNMT1 encodes a protein comprising 1.632 amino acids, possibly associated with carcinoma development." (PMID 39335135, 2024). "Blocking cytidine deaminase supported degradation of the DNMT1 protein in cancer cell lines (range 82–90%), even though decitabine treatment alone of cancer cells caused a small but significant increase in DNMT1 mRNA expression." (PMID 37208732, 2023).
cancer (continued). "Accumulating evidence has implied that aberrant expression of DNMT1 causes alteration of the DNA methylation pattern, which is linked to the occurrence and development of several cancers." (PMID 37510229, 2023). "Often, this downregulation is caused by hypermethylation of their promoter region by the DNA methyltransferase 1 (DNMT1) that is overexpressed in several cancer." (PMID 35279198, 2022). "A mounting body of evidence suggests that downregulation of DNA methyltransferase 1 (Dnmt1) expression would lead to increased mutation rates and cancer development." (PMID 35205097, 2022). "Recent data have implicated a role for the downregulation of DNMT1 in the invasive and migratory potential of some cancer cells." (PMID 35578613, 2022). "Several genes and gene products were identified as targets of miR-223, including NLRP3, IL18, IL1β, DNA methyltransferase 1, and checkpoint kinase-1, signifying its potential use as a cancer-specific diagnostic biomarker and therapy." (PMID 35205115, 2022). "Kaplan-Meier plots indicate significant association between DNMT1 expression levels in cancer cells and their stromal fibroblasts and patient’s overall survival (OS) (P = 0.0029 and P = 0.01091, respectively)." (PMID 35719957, 2022). "Chromosome specific retention of cancer associated DNA hypermethylation following pharmacological inhibition of DNMT1 is shown, with residual CpG methylation on the X chromosome compared to autosomes, suggesting a separate mechanism of methylation." (PMID 35654826, 2022). "On the contrary, the hypermethylation of promoter CpG islands of TSGs due to the overexpression of DNMT1 is a popular mechanism of gene silencing and a hallmark of cancer." (PMID 35898303, 2022). "The host gene DNMT1 is a crucial regulator of genomic methylation, which mediates DNA methylation of various cancer-associated genes in regulation of metastatic propensity." (PMID 35418185, 2022). "It has been observed that globally hypomethylated mice expressing a single hypomorphic DNMT1 allele develop cancer, suggesting that altered DNA methylation can cause cancer." (PMID 35078341, 2022). "In this study, we utilized online tools and databases for pan-cancer and HNSCC analysis of DNMT1 expression and its association with clinical cancer characteristics." (PMID 33500531, 2021). "Numerous studies have found that DNMT1 is associated with abnormal DNA methylation, and elevated expression of DNMT1 has been shown to promote the occurrence and development of cancers of the esophagus, breast, pancreas, thyroid, and colon." (PMID 34749775, 2021). "DNMT1 is necessary to maintain methylation in the genome and has also been linked to several human diseases, ranging from cancer to neurological abnormalities." (PMID 34439147, 2021). "Aberrant DNA methylation is a hallmark of cancer cells, and the enzyme DNA methyltransferase 1 (DNMT1) represents a recognized target in cancer treatment." (PMID 33800819, 2021). "The DNMT1 up-regulation was also revealed in most cancer-associated fibroblasts in relation to their corresponding adjacent normal fibroblasts." (PMID 33498667, 2021). "Considering the pleiotropic nature of PPARγ and DNMT1 there is a need to investigate if their interaction also plays a role in the association between metabolism and cancer." (PMID 34439147, 2021). "PPARγ–DNMT1 co-expression is associated with several cancers while the evolutionary action (EA) score revealed PPARγ variants to be more of an oncogenic type." (PMID 34439147, 2021). "Several studies show that suppressed DNMT1 expression caused cell cycle delay and cancer-germline gene activation." (PMID 34572918, 2021). "Horizontal analysis indicated that TET2, DNMT3B, DNMT3A, and DNMT1 demonstrated much higher mutation frequency among 33 cancers." (PMID 34325709, 2021). "It has been shown that dysregulation of DNMT1 associates with tumorigenesis and progression of multiple types of cancer." (PMID 33500531, 2021).
cancer (continued). "In cancer, DNA methyltransferases such as DNMT1 and histone methyltransferases such as EZH2 are associated with low tumor-infiltrating CD8+ T cells and patient outcomes." (PMID 32708698, 2020). "DNA methyltransferase 1 (DNMT1) is a cytosine methylase that is important for normal mammalian development, and DNMT1 mutations are correlated with human cancer." (PMID 31660426, 2019). "For example, reducing DNMT1 activity using hypomorphic alleles protects against cancer formation in ApcMin mice." (PMID 31306451, 2019). "Here we present evidence that while addition of 2i broadly downregulates UHRF1 and DNMT1 in various cancer cells, distinct underlying mechanisms are involved." (PMID 30696879, 2019). "Two recent studies have also examined the effects of DNMT1 mutation on DNA methylation and gene transcription in human, albeit in cancer cells." (PMID 29598829, 2018). "It has also been shown that dysregulation of host methylation by HPV16 E6 and E7 by upregulation of DNMT1 expression is associated with host immune suppression during HPV-associated cancer progression." (PMID 30360578, 2018). "We used subgroup analyses to explore the effects of different cancer types and genotyping methods on the associations of increased risk of cancer with the DNMT1 rs16999593 (T/C) and rs2228611 (G/A) polymorphisms." (PMID 28473984, 2017). "Odd ratios and 95% confidence intervals were used to evaluate the strength of association between three DNMT1 polymorphisms and cancer risk." (PMID 28473984, 2017). "Subsequently, a number of studies have concentrated on the relationships between DNMT1 polymorphisms and risks of different cancers." (PMID 28473984, 2017). "The DNMT1 rs2228612 (A/G) polymorphism was significantly related to cancer risk in the recessive model." (PMID 28473984, 2017). "The aim of this meta-analysis is to elucidate the associations between DNMT1 polymorphisms and cancer susceptibility." (PMID 28473984, 2017). "Until now, no meta-analysis has been carried out to investigate the relation of the three DNMT1 polymorphisms (rs16999593 (T/C), rs2228611 (G/A), and rs2228612 (A/G)) with risk of cancer." (PMID 28473984, 2017). "This meta-analysis elucidated that the DNMT1 rs16999593 (T/C) polymorphism was associated with different cancer types." (PMID 28473984, 2017). "DNMT1 is crucial for the maintenance of DNA methylation, which causes gene silencing and is known to regulate many cancer-related genes including many tumor suppressors." (PMID 28212608, 2017). "In this meta-analysis, we found that DNMT1 rs2228612 (A/G) was associated with risk of overall cancer in the recessive model." (PMID 28473984, 2017). "The links of EZH2 and DNMT1, the two epigenetic regulators and oncogenes, have been shown to be associated with tumorigenesis and cancer progression in several other studies." (PMID 28360411, 2017). "In a most recent report, the gene locus of DBCCR1 has been associated with DNMT1 activity in cancer." (PMID 28427182, 2017). "Following this rationale, it is of critical importance to investigate if DNMT1 is necessary for the stimulated cancer cell growth and invasion in DBCCR1-deficient cells." (PMID 28427182, 2017). "Previous studies have reported that SNPs of DNMT1 gene are associated with susceptibility to cancers such as ovarian cancer and breast cancer." (PMID 27087738, 2016). "Aberrant expression of DNMT1 is associated with unfavorable prognosis of various cancers including GC." (PMID 27087738, 2016). "To investigate crosstalk between KDM1A and DNMT in cancer cells, we took advantage of previous observations on mouse ES cells, where DNMT1 has been shown to associate with KDM1A." (PMID 27449289, 2016). "In comparison with normal cells, the levels of DNMT1 are often aberrantly increased in cancer cells, causing transcriptional silencing of tumor suppressor genes by hypermethylation of their promoter CpG-rich regions." (PMID 27525019, 2016).